LYZL1 (lysozyme like 1)
Synonyms: LYC2; MGC33408; KAAG648; LYZD1; PRO1278; bA534G20.1
Tractability: Antibody: UniProt places it where antibodies can reach, with high confidence; UniProt predicts a signal peptide or a membrane-spanning region; its Gene Ontology location is reachable by antibodies, with medium confidence.
Gene: Protein-coding gene on chromosome 10 (29,289,061 to 29,318,328, forward strand). Ensembl gene ENSG00000120563.
Subcellular location: Secreted
Gene Ontology:
Molecular function: lysozyme activity
Cellular component: extracellular region
Genetic constraint (gnomAD): Loss-of-function variants: 18 observed, 15.01 expected, observed/expected ratio (o/e) 1.2, 90% interval 0.83 to 1.74. The upper end of that interval is the gene's LOEUF score, 1.74, which puts it in group 6 of 6, group 1 being the genes least tolerant of losing a copy. Missense variants: 117 observed, 147.31 expected, observed/expected ratio (o/e) 0.79, 90% interval 0.68 to 0.93. Synonymous variants: 46 observed, 60.97 expected, observed/expected ratio (o/e) 0.75, 90% interval 0.6 to 0.96.
Homologues: Orthologues: chimpanzee LYZL1 (100% identical), mouse Lyzl1 (76% identical), rat Lyzl1 (68% identical), rabbit LYZD1 (59% identical), zebrafish lyz (45% identical), Drosophila melanogaster CG30062 (34% identical), Drosophila melanogaster LysD (34% identical), Drosophila melanogaster LysE (34% identical), Drosophila melanogaster CG11159 (34% identical), Drosophila melanogaster LysB (34% identical), Drosophila melanogaster LysP (34% identical), Drosophila melanogaster LysS (34% identical), and 4 more. Paralogues in human: LYZL2 (97% identical), LYZ (45% identical), SPACA5 (45% identical), SPACA5B (45% identical), SPACA3 (43% identical), LYZL4 (39% identical), LYZL6 (38% identical), LALBA (32% identical).
Diseases named in the same sentence as LYZL1 in open-access papers:
LYZL1 is named in the same sentence as 10 diseases in open-access papers, as found by Europe PMC text mining. Sharing a sentence is not in itself a finding about the gene and the disease. The quoted sentences say what the papers report.
Azoospermia (1 paper, 2025). Absence of any measurable level of sperm,whereby spermatozoa cannot be observed even after centrifugation of the semen pellet. "Additionally, EDDM3B and LYZL1 were linked to spermatogenic failure, EDDM3B and CCDC90B with azoospermia, and EDDM3B with oligoasthenoteratozoospermia." (PMID 40497989, 2025).
IgA nephropathy (1 paper, 2023). "In IgA nephropathy, LYZL1 and SIPA1L3 risk genotypes are related to the decrease of Dialister and Bacilli and the risk genotypes of PLTP and AL365503.1 were associated with increased abundance of Erysipelotrichaceae and Lachnobacterium." (PMID 38189041, 2023).
liver cancer (1 paper, 2023). An epithelial or non-epithelial malignant neoplasm that arises from the liver. "The expression of the LYZL1 protein has been detected in a small number of cancer tissues, mainly ovarian and liver cancers, and not in lymphomas." (PMID 37345090, 2023).
cancer (1 paper, 2023). A tumor composed of atypical neoplastic, often pleomorphic cells that invade other tissues. "Overall, its role in disease or cancer has not been characterized, while the potential role of LYZL1 in anticancer drug resistance has been suggested." (PMID 37345090, 2023).
LYZL1 also shares sentences with these, for which no sentence is quoted: Crohn disease (1 paper); IgA vasculitis (1); lymphoma (1); oligoasthenoteratozoospermia (1); orofacial cleft (1); ovarian carcinoma (1).